TCTA (T cell leukemia translocation altered)
Description:
May be required for cellular fusion during osteoclastogenesis.
Tractability: Antibody: UniProt predicts a signal peptide or a membrane-spanning region.
Gene: Protein-coding gene on chromosome 3 (49,412,212 to 49,416,476, forward strand). Ensembl gene ENSG00000145022.
Subcellular location: Membrane
Subcellular location (Human Protein Atlas): Cytosol
Gene Ontology:
Molecular function: protein binding
Biological process: negative regulation of osteoclast differentiation; osteoclast fusion
Cellular component: membrane
Genetic constraint (gnomAD): Loss-of-function variants: 13 observed, 14.34 expected, observed/expected ratio (o/e) 0.91, 90% interval 0.59 to 1.44. The upper end of that interval is the gene's LOEUF score, 1.44, which puts it in group 5 of 6, group 1 being the genes least tolerant of losing a copy. Missense variants: 138 observed, 140.21 expected, observed/expected ratio (o/e) 0.98, 90% interval 0.86 to 1.13. Synonymous variants: 58 observed, 63.27 expected, observed/expected ratio (o/e) 0.92, 90% interval 0.74 to 1.14.
Homologues: Orthologues: rabbit TCTA (99% identical), rat Tcta (94% identical), pig TCTA (92% identical), mouse Tcta (91% identical), dog TCTA (89% identical), guinea pig TCTA (83% identical), macaque TCTA (75% identical), zebrafish tcta (50% identical), tropical clawed frog tcta (50% identical).
Diseases named in the same sentence as TCTA in open-access papers:
TCTA is named in the same sentence as 6 diseases in open-access papers, as found by Europe PMC text mining. Sharing a sentence is not in itself a finding about the gene and the disease. The quoted sentences say what the papers report.
anorexia nervosa (1 paper, 2025). A disorder most often seen in adolescent females characterized by a refusal to maintain a minimally normal body weight, an intense fear of gaining weight, a disturbance in body image, and, in postmenarcheal females, the development of amenorrhea. "In addition, SMG9 in AD, TCTA in anorexia nervosa, RHOA and IMPDH2 in intelligence, CRHR1 in PD, and PHF7 in schizophrenia are all reported to be conserved among a wide range of species, although their relations with the corresponding traits remain to be explored." (PMID 39905509, 2025).
dyslexia (1 paper, 2025). A learning disorder characterized by an impairment in processing written words. "Four genes – SORCS3, TCTA, TRAIP and AMT – shown to be pleiotropic had previously been associated with dyslexia and ADHD in individual GWAS studies and are very strong pleiotropic candidate genes." (PMID 39009701, 2025).
tumor (2 papers, 2017 to 2018). "Regarding CNAs present in 419 tumour suppressor genes, losses of the most common CNA tumour suppressor genes are found at 3p21.31 specified by genes RBM6 in 35 HRO-, RBM5 in 30 HRO-, LIMD1 in 28 HRO-, TCTA in 26 HRO- and at 3p22.2 by MLH1 in 33 HRO-tumours." (PMID 28486536, 2017).
neurodegenerative disease (1 paper, 2025). A disorder of the central nervous system characterized by gradual and progressive loss of neural tissue and neurologic function. "Other genes such as SPI1, LRRC37A, NSF, and TCTA have also been reported to have effect on neurodegenerative diseases." (PMID 39905509, 2025).
TCTA also shares sentences with these, for which no sentence is quoted: pancreatic adenocarcinoma (1 paper); schizophrenia (1).